CCL22 (C-C motif chemokine ligand 22)
Diseases named in the same sentence as CCL22 in open-access papers (continued):
Sharing a sentence is not in itself a finding about the gene and the disease.
tumor (continued). "Furthermore, CCL22 has been found to stimulate DGKα activity in tumor cells, suppressing NADPH oxidase 4 (NOX4) and averting cisplatin-induced ROS overproduction." (PMID 39286635, 2024). "These include increased tumor expression of CCR7 that indicates poor prognosis in mccRCC patients treated with TKIs and increased CXCR4, CXCL5, CCL4, CCL22, and IL-1, which have been linked to poor outcomes by promoting high proliferation rates/aggressive phenotypes." (PMID 38067341, 2023). "If the tumor volume shrinks or stagnates during treatment, the level of CCL22 may decrease accordingly." (PMID 36969873, 2023). "Remarkably, CCR4 expression was increased in Foxp3UP CD8 T cells, and in transwell assays these cells exhibited enhanced migration toward CCL22, which suggests that the CCL22/CCR4 axis may play a role in their tumor recruitment." (PMID 36045586, 2023). "Several genes such as Csf2, Has1, Ccl22 and Tnf induced by ruxolitinib and inhibited by IKK-16 are associated with driving tumor-promoting functions in macrophages and increasing survival of tumor cells." (PMID 37005447, 2023). "Similarly, CCL17 and CCL22 secreted by M2 macrophages and tumor cells recruit Tregs to the TME, thereby inhibiting anti-tumor immunity." (PMID 37568390, 2023). "Interestingly, in the MIP treated group tumor infiltrating immune cells had about 60% reduction in the mRNA level of Ccl22 in comparison to control group." (PMID 37122749, 2023). "CCL22 has a relatively high level in the early stage of tumor development." (PMID 36969873, 2023). "CCL21, CCL22, and CCL24 are genes encoded by C–C motif chemokine ligands, which are components of intercellular communication and essential in the functioning of the tumor microenvironment." (PMID 37537613, 2023). "A mouse model confirmed that CD79A allows bone marrow-derived suppressor cells to maintain their immature state, enhances the ability to suppress T-cell proliferation, stimulates their migration, and induces the secretion of protumor cytokines such as IL-6 and CCL22, thereby promoting tumor growth." (PMID 37344840, 2023). "This could in part be mediated via the increased CCL22 levels detected in the tumor supernatants upon Flt3L treatment." (PMID 37622122, 2023). "When the chemokine CCL22, produced by macrophages, as well as tumor cells of ovarian cancer, is secreted, regulatory T cells are further clustered to suppress T cell-mediated immune response against tumor cells, thus creating an environment that promotes cancer growth." (PMID 36674491, 2023). "It has been reported that tumor-derived CCL22 can recruit Treg cells and promote tumor development." (PMID 36969873, 2023). "CC chemokine receptor 4 (CCR4), with two ligands, CCL17 and CCL22, is a key chemokine receptor selectively expressed on normal T cells that mediates the entry of regulatory T cells into the tumor microenvironment, and it is mainly expressed in tumor-infiltrated Treg cells." (PMID 36992198, 2023). "Recent studies have shown that CCL22 can recruit trophoblast cells to support B-cell maturation; CCL22 may also potentially have a nursing-like effect in the tumor development." (PMID 36969873, 2023). "Since Gli1 is the important tumor‐promoting transcriptional factor and therapeutic target, we utilized the Gli‐dependent luciferase reporter system for evaluating effects of TAMs‐released CCL22 on the intratumoral Gli1 activity and its nuclear location." (PMID 37846367, 2023). "In addition, Cd81+migcDC1 also expressed high levels of Ccl22, which has been shown to promote the interaction with Tregs and CCL22 was also increased at the protein level in the tumor upon 9 days of Flt3L treatment." (PMID 37622122, 2023). "So, the inference from our data is that MIP significantly suppresses the expression of CCL22 on tumor infiltrating immune cells which could be responsible for the impaired (reduced) trafficking of Tregs from the circulation into TME." (PMID 37122749, 2023).
tumor (continued). "Modifying the tumor microenvironment, possibly through CCL22 or CCR4 inhibition, may deter Treg recruitment." (PMID 38115302, 2023). "Notably, CCL22 levels were also increased in the tumor supernatants 48h after αCD40 monotherapy and further increased in αCD40+Flt3L-treated tumors." (PMID 37622122, 2023). "Indeed, it has previously been shown that tumor CCL22 can result in Treg attraction to the tumor and that CCL22 promotes DC-Treg interactions." (PMID 37622122, 2023). "Since, DCs are reported to be the exclusive source of homeostatic CCL22 in the lymph node, we isolated CD11c+ DCs from tumor draining lymph node using a pan DC isolation kit and did quantitative RT-PCR analysis of expression of Ccl22 on these DCs whose purity was ~80%." (PMID 37122749, 2023). "PMs can be switched to tumor-associated macrophages (TAMs) in ascites with pro-tumor effect by releasing various soluble mediators, including IL-6, IL-10, CCL18, CCL22, TNF-α, TGF-β, and EGF that triggers pro-tumorigenic signaling pathways in tumor cells and infiltrating leukocytes in the TME." (PMID 37932814, 2023). "In addition, CCL22 can also be induced in tumor infiltrating immune cells by interleukin-1 (IL-1α) derived from cancer cells." (PMID 35176085, 2022). "Importantly, VS-6063 more effectively inhibited tumor malignancy in the CCL22-treated group than in the PBS-treated group." (PMID 35962191, 2022). "Furthermore, the ESTIMATE analysis indicated that the high-CCL22-expression subgroup had a higher immune/stromal/estimate score and lower tumor purity." (PMID 35295948, 2022). "Some studies argue that CCL22 is mainly derived from tumor cells." (PMID 35805111, 2022). "For example, CCL22 could attract regulatory T cells (T-reg) into tumor mass and decrease cell immunity in ovarian cancer." (PMID 35805111, 2022). "However, the direct stimulatory effect of CCL22 on intratumoral signaling and tumor malignancy is less understood." (PMID 35962191, 2022). "Depending on the particular EBV+ tumor type, this CCL17 and CCL22 expression could be coming from the tumor cells themselves, infiltrating host immune cells, or a combination of the two." (PMID 35025968, 2022). "The production of CCL22 by cannabigerol-treated metastatic cells could provide a method by which the T lymphocytes could be recruited into the tumour site." (PMID 36923728, 2022). "M2 macrophages could promote tumor invasion through epithelial mesenchymal transformation induced by CCL22." (PMID 36157211, 2022). "We excitedly found that the immune/stromal/estimate scores were significantly higher, while tumor purity was significantly lower in the high-CCL22-expression subgroup compared to the low-CCL22-expression subgroup, which suggested that CCL22 was closely related to TME." (PMID 35295948, 2022). "Upon expansion of abnormal tumor blood vessels, hypoxic microenvironment in tumors leads to the upregulation of chemokine (C-C motif) ligand-22 (CCL-22) and chemokine (C-C motif) ligand-28 (CCL-28), which are both involved in the recruitment of Tregs into tumors." (PMID 36439137, 2022). "Additionally, TAMs shortened the survival time of tumor-bearing animals, whereas the anti-CCL22 Ab was able to attenuate this effect." (PMID 35962191, 2022). "CCL22 recruits Treg cells in the tumor microenvironment (TME) and treg cells could competitively bind with cytotoxic lymphocyte (CTL), thereby inhibiting the proliferation of CTL and contributing to immune suppression." (PMID 35396377, 2022). "Additionally, the percentage of CD4+FOXP3+ Tregs in tumor tissues exhibited a significant positive association with L1CAM and CCL22 in patients with ESCC." (PMID 33710805, 2021). "CCL22 further promotes the recruitment of Tregs into tumor sites." (PMID 33710805, 2021). "Therefore, they are recruited into the TME in response to CCL22, a chemokine that is produced by TAMs and primary tumor cells." (PMID 34575965, 2021).
tumor (continued). "Blocking the CCL22-mediated recruitment of CCR4+ Tregs may provide a potential strategy to control tumor growth." (PMID 33710805, 2021). "Thus, TGFb-mediated miR-34a downregulation in HCC led to an increase in CCL22 and, consequently, to regulatory T cell recruitment to create an immunosuppressive tumor environment." (PMID 34422814, 2021). "In the tumor tissues, CCL17 and CCL22 are mainly secreted by macrophages and tumor cells." (PMID 34885241, 2021). "Importantly, the high levels of CCL22 in supernatants of PIC-treated tumor samples were significantly decreased upon combination with curcumin." (PMID 33809574, 2021). "In addition, different kind of chemokines from M2-like macrophages including CCL18 and CCL22 mediate immune cells migration to tumor microenvironment." (PMID 34194433, 2021). "Likewise, tumor cells and tumor-infiltrating macrophages (TAMs) produce the chemokine CCL22, which attracts regulatory T cells (Tregs) to create an immune-suppressive microenvironment, thereby impairing anticancer immunity." (PMID 33776764, 2021). "In addition, there was a trend for a positive correlation of IL-8 and IP-10/CXCL10 with perivascular CD163+ cell infiltrates as well as a trend for a positive correlation of the percentage of CD163+ cells and MDC-1/CCL22 in the tumor core." (PMID 34654395, 2021). "Therefore, we determined the expression levels of CXCL-9, CXCL-10, CCL-17, and CCL-22 in tumor tissues." (PMID 34620867, 2021). "The prognostic value of CCL17 and CCL22 expression also depends on the tumor type." (PMID 34503058, 2021). "Furthermore, CCL22 promoted Treg recruitment to the tumor site; the Tregs then secreted TGF-β, which in turn promoted L1CAM expression via Smad2/3 in a positive feedback loop." (PMID 33710805, 2021). "We found that CCL22 expression was higher in ESCC tumor tissues than in adjacent normal tissues." (PMID 33710805, 2021). "In addition, TAMs, monocytic-MDSCs, polymorphonuclear-MDSCs, and TANs can produce the CCR4 ligands CCL17 and CCL22 in tumor tissues, contributing to tumor progression by recruiting CCR4-expressing Treg cells." (PMID 34885241, 2021). "NK cells secrete CCL22 to recruit Tregs via CCR4 within the tumor and it may intensify the level of immune-inhibition." (PMID 34177887, 2021). "The combination treatment caused increased secretion of CCL2, CCL21, CXCL1, CXCL2, CXCL5, CXCL9 and CXCL16, whereas the levels of CCL11, CCL17, CCL19, CCL22, CCL25, CCL27 and CX3CL1, which are associated with protumourigenic effects, were decreased in the tumours." (PMID 33014356, 2020). "CCL17 and CCL22 are well established in recruiting Treg cells and favoring tumor outgrowth." (PMID 33252851, 2020). "We also show changes in DCs, where Siah2 loss increased expression of the IFNγ-induced chemokine Cxcl9, which recruits effector T cells to a tumor site, and concomitantly decreased expression of Ccl17 and Ccl22, chemokines that contribute to recruitment of Tregs to tumors." (PMID 31911617, 2020). "On performing a microarray analysis of cytokines, chemokines, and receptors, we found that, among others, CXCL10 was up-regulated in Tα1-DC as compared with GM-DC and FL-DC, whereas CCL22 was apparently down-regulated, consistent with the results obtained at the tumor site." (PMID 32817121, 2020). "Tumor associated macrophages (TAMs) and myeloid suppressor cells (MDSCs) release chemokines, such as CCL17, CCL22, CCL5, CCL6 or CCL28, depending on the tumor type, to attract Tregs expressing the chemokine receptors CCR4, CCR5, CCR10 and CXCR3 from secondary lymphoid tissues to the tumor." (PMID 32937953, 2020). "In contrast, CCL22, abundantly expressed in many types of cancer and instrumental for intratumoral recruitment of Treg, was down-regulated by Tα1 in DC and at the tumor site." (PMID 32817121, 2020).
tumor (continued). "For example, the expression of the M2-type chemokine CCL22 through the NF-κB pathway in M2 macrophages is downregulated by Fucoidan, which may inhibit tumor cell migration and regulatory T cell recruitment." (PMID 32059469, 2020). "CCL17 and CCL22 are both produced by cancer cells in a tumor and by TAM." (PMID 33182504, 2020). "Notably, administration of CCL17 and CCL22 antibodies led to a 30% inhibition in tumor weight relative to treatment with control antibody." (PMID 31911617, 2020). "The roles of p65/miR‐23a/CCL22 axis was then investigated in the xenograft tumor models." (PMID 31769216, 2020). "CCL22 is secreted by M2 macrophages which promoted tumor development and migration of cancer cells." (PMID 32256661, 2020). "However, CCL22-expressing TAMs and tumor cells can be targeted and perished by CCL22-specific T cells." (PMID 32499786, 2020). "Altogether, we concluded that p65 overactivation could repress miR‐23a expression, leading to CCL22 disinhibition and subsequent promote tumor growth." (PMID 31769216, 2020). "The presence of extensive tumor-associated macrophage infiltration into the RCC microenvironment contributes to cancer progression and metastasis by stimulating angiogenesis, tumor growth, cellular migration and invasion, as well as recruitment of Tregs to the tumor site by secreting CCL20 or CCL22." (PMID 35582435, 2020). "The nanosystem abrogated IL expression, shut down after CCL22 secretion, and restricted Treg cell accumulation within the tumor site to induce sufficient antitumor immune responses (i.e., activated sufficient CD8+ T cells, IFN-γ, and TNF-α) with X- and NIR-induced therapeutic effects." (PMID 31660068, 2019). "Since CCL22 attracts CCR4+ lymphocytes, such as CTCL cells, Tregs, and Th2 cells, the decrease in CCL22 might suppress the development of tumor mass in vivo." (PMID 31616630, 2019). "Therefore, HBV infection and activation of the TGF-β-miR-34a-CCL22 axis facilitates portal vein tumor thrombus development of HBV-positive HCC through the creation of an immune-subversive microenvironment." (PMID 31349837, 2019). "Furthermore CCR4 (receptor for CCL17 and CCL22) antagonists have been shown to decrease the tumor-promoting environment." (PMID 30850664, 2019). "Accumulating studies indicate that CCL22 plays a tumor-promoting role in human cancer." (PMID 31842422, 2019). "In addition to promoting tumour progression, by controlling Treg recruitment via CCL22 signalling, however, IL-1A mediated IL-1R1 signalling has also been reported to have anti-tumour functions." (PMID 29760166, 2018). "In GBM tumor cells, secreted soluble factors including CCL22 can facilitate the recruitment and retention of Tregs in the tumor microenvironment, and the amount of Tregs demonstrated an inverse correlation with patient survival, although it was not statistically significant." (PMID 29867979, 2018). "The subset of genes upregulated in lungs of both tumor free and metastatic Ikkβ-deficient animals comprised Tnfa, Ccl5, Ccl17, Ccl22, Cxcl1 and Csf2, although not all changes reached significance." (PMID 29682184, 2018). "Possible differences in the expression pattern of CCR4 on tumor cells vs lymphocytes might be one of the reasons as CCL22 is reported to have higher affinity for CCR4-expressing lymphocytes." (PMID 28415693, 2017). "To test the effects of beta blockers on the chemokine environment in tumors of RRS-exposed animals, we examined the expression of genes that are characteristic of either immune suppression (Foxp3, CCL22) or effector anti-tumor immunity (Granzyme B, CCL5, IFN-γ, CXCL9, CXCL10 and CXCL11)." (PMID 28603578, 2017). "Also, IL-27-releasing DCs induced a proper microenvironment for cancer growth, since IL-27 promoted CCL22 production and consequently mediated the recruitment of Tregs to the tumor site." (PMID 29033934, 2017). "CCL22 is one of CC chemokines produced by macrophages, dendric cells and tumor cells." (PMID 28086903, 2017).
tumor (continued). "To further understand the role of adaptive immunity in the tumor tissue, we investigated the impact of RRS on tumor weight and on immune suppression markers (Foxp3, CCL22), as well as markers for anti-tumor immunity (Granzyme B, CCL5, IFN-γ, CXCL9, CXCL10 and CXCL11)." (PMID 28603578, 2017). "Small molecule compounds and antibodies with the capacity to block CCL17-and CCL22-mediated recruitment of Th2 cells and Treg cells have been shown to produce positive effects in various disease models for asthma, atopic diseases, and tumor growth." (PMID 29099057, 2017). "Therefore, we investigated the expression of Arg1, Fizz, Msr2, CCL3, CCL22 mRNA in tumor cells using RT-qPCR." (PMID 29137420, 2017). "As the quantity and activity of TAMs could be explained by the expression of Arg1, Fizz1, Msr2, CCL3, CCL22, and so the mRNA levels of these factors in tumor tissues were detected." (PMID 29137420, 2017). "We discovered that the tumor cells and Treg cells migration were all inhibited in the conditioned medium from the fucoidan-pretreated M2 macrophages due to the lower concentration of CCL22." (PMID 27775051, 2016). "It has been recently shown that CCL22 directly induce tumor cells migration." (PMID 27775051, 2016). "We found that fucoidan significantly inhibited CCL22 expression in M2 macrophages via NF-κB pathway and further regulated tumor cells migration and lymphocytes recruitment which may represent a new mechanism for fucoidan in antitumor activity." (PMID 27775051, 2016). "Interestingly, outside of the tumor parenchyma and microenvironment, circulating CCL22 appears to be depressed in the sera of patients with malignant gliomas." (PMID 26217588, 2015). "It was also interesting whether changes in the concentration of CCL22 and the percentage of Tregs may depend on the stage, grade, and histological type of the tumor." (PMID 25647263, 2015). "The therapeutics of possible underlying mechanisms are the improvement of the tumor microenvironment through the suppression of NF-κB and subsequent cytokines such as TGF-β, IL-10, VEGF, COX-2, CCL2 and CCL22, and enhancement the function of transferred CD8+ T-cells." (PMID 26683520, 2015). "Collectively, these findings provide compelling evidence, which suggests that higher accumulation of Treg cells in local tumor maybe a consequence of elevated levels of CCL22 in the tumor microenvironment attracting CCR4-expressing Treg cells." (PMID 26020249, 2015). "There were also significant differences in the PF CCL22 levels based on tumor histology." (PMID 25647263, 2015). "The TGF-β - miR-34a - CCL22 axis is therefore important in modulating the tumor microenvironment." (PMID 25743773, 2015). "Moreover, the authors have shown that tumor Tregs express functional CCR4, the receptor for CCL22, and can migrate to CCL22, present in the tumor microenvironment." (PMID 25647263, 2015). "Through the release of CCL22/CCR4 and PGE2 or H-ferritin, tumor cells, including those in hematologic malignancies, cause attraction and expansion of Treg cells to the tumor site and in peripheral blood (PB), thereby increasing Treg cells in the tumor microenvironment and in PB." (PMID 25793623, 2015). "All tumor cells, monocytes/macrophages, and mDCs produce CCL22 to recruit Tregs via the GPCR CCR4." (PMID 25110692, 2014). "It was also shown that the circulating T-regulatory cells display significantly higher expression of CCR4 than the tumor infiltrating T-regulatory cells suggesting that they could be recruited via the CCR4/CCL22 axis." (PMID 24384839, 2013). "It was identified that tumor secretion of CCL22 was positively correlated with the intratumoral Treg infiltration (P<0.0001), but its association with lymphoid aggregates surrounding the tumor was not proven to be significant (P=0.056)." (PMID 24124553, 2013).